IFI27L1 (interferon alpha inducible protein 27 like 1)
Description:
Plays a role in the apoptotic process and has a pro-apoptotic activity.
Synonyms: ISG12C; FAM14B
Tractability: Antibody: UniProt predicts a signal peptide or a membrane-spanning region.
Gene: Protein-coding gene on chromosome 14 (94,081,271 to 94,103,846, forward strand). Ensembl gene ENSG00000165948.
Subcellular location: Membrane
Gene Ontology:
Molecular function: protein binding; molecular adaptor activity
Biological process: apoptotic process; intrinsic apoptotic signaling pathway
Cellular component: mitochondrial membrane; membrane
Genetic constraint (gnomAD): Loss-of-function variants: 3 observed, 8.67 expected, observed/expected ratio (o/e) 0.35, 90% interval 0.16 to 0.89. That is too few expected variants to judge how well the gene tolerates losing a copy. Missense variants: 107 observed, 123.83 expected, observed/expected ratio (o/e) 0.86, 90% interval 0.74 to 1.01. Synonymous variants: 46 observed, 45.39 expected, observed/expected ratio (o/e) 1.01, 90% interval 0.8 to 1.3.
Homologues: Orthologues: macaque IFI27L1 (73% identical), zebrafish ifi27.4 (47% identical), zebrafish ifi27.6 (46% identical). Paralogues in human: IFI27L2 (62% identical), IFI27 (56% identical), IFI6 (40% identical).
Diseases named in the same sentence as IFI27L1 in open-access papers:
IFI27L1 is named in the same sentence as 8 diseases in open-access papers, as found by Europe PMC text mining. Sharing a sentence is not in itself a finding about the gene and the disease. The quoted sentences say what the papers report.
viral infections (2 papers, 2021 to 2025). "IFNα-inducible protein 6 (IFI6, aka IFI-6-16, or GIP3) is a member of a conserved protein family that consists of IFI6, IFI27 (ISG12a), IFI27L1 (ISG12c), and IFI27L2 (ISG12b), and it was first characterized as a cellular gene induced by the IFN response and virus infections." (PMID 34205058, 2021).
tumor (1 paper, 2021). "The heatmap showed that 12 tumor suppressors formed into two clusters: cluster 1 contains seven downregulated tumor suppressors including PTEN, PSME1, DNAJB1, HSPH1, DEDD2, PAK1IP1, and MIR1244-3; and cluster 2 contains five upregulated tumor suppressors (OSGIN1, IFI27L1, MTCH2, NKD2, and IBTK)." (PMID 34571936, 2021).
IFI27L1 also shares sentences with these, for which no sentence is quoted: Autoimmunity (1 paper); Cirrhosis (1); Immunodeficiency (1); infection (1); multiple sclerosis (1); neurological disease (1).